CYB5D1 (cytochrome b5 domain containing 1)
Description:
Radial spoke stalk protein that binds heme under oxidizing conditions. Required for the coordinated beating of multiple cilia maybe by functioning in a redox signaling pathway.
Synonyms: FLJ32499
Tractability: Small molecule: a structure with a bound ligand is known. PROTAC: ubiquitination databases record sites on it.
Gene: Protein-coding gene on chromosome 17 (7,857,746 to 7,862,282, forward strand). Ensembl gene ENSG00000182224.
Subcellular location: Cytoplasm, cytoskeleton, cilium axoneme
Subcellular location (Human Protein Atlas): Golgi apparatus; Nucleoli
Gene Ontology:
Biological process: cilium movement; flagellated sperm motility; regulation of cilium beat frequency
Cellular component: 9+2 motile cilium; axoneme; cilium; radial spoke; sperm flagellum
Genetic constraint (gnomAD): Loss-of-function variants: 30 observed, 25.73 expected, observed/expected ratio (o/e) 1.17, 90% interval 0.87 to 1.58. The upper end of that interval is the gene's LOEUF score, 1.58, which puts it in group 6 of 6, group 1 being the genes least tolerant of losing a copy. Missense variants: 265 observed, 310.87 expected, observed/expected ratio (o/e) 0.85, 90% interval 0.77 to 0.94. Synonymous variants: 128 observed, 126.52 expected, observed/expected ratio (o/e) 1.01, 90% interval 0.88 to 1.17.
Homologues: Orthologues: chimpanzee CYB5D1 (100% identical), macaque CYB5D1 (99% identical), rabbit CYB5D1 (89% identical), dog CYB5D1 (88% identical), guinea pig CYB5D1 (88% identical), pig CYB5D1 (88% identical), rat Cyb5d1 (85% identical), mouse Cyb5d1 (83% identical), zebrafish cyb5d1 (63% identical), tropical clawed frog cyb5d1 (59% identical), Drosophila melanogaster CG15429 (32% identical).
Diseases named in the same sentence as CYB5D1 in open-access papers:
CYB5D1 is named in the same sentence as 6 diseases in open-access papers, as found by Europe PMC text mining. Sharing a sentence is not in itself a finding about the gene and the disease. The quoted sentences say what the papers report.
breast carcinoma (1 paper, 2009). "In summary, the findings summarized above indicate that CYB5D1 is an important but currently not well known survival gene in breast cancer with potential diagnostic and therapeutic value." (PMID 19851466, 2009). "The down-regulation of CYB5D1 colon cancer is consistent with its role of a survival gene in breast cancer." (PMID 19851466, 2009). "However, the findings related to PGRMC1 may help to elucidate the molecular mechanisms through which CYB5D1 reduced the malignant potency of breast cancer cells." (PMID 19851466, 2009). "The case of CYB5D1 suggests that the absence of key risk or survival genes from some microarray platforms may in general be a major limiting factor in data merging, demonstrated here on the specific example of survival prediction for breast cancer patients." (PMID 19851466, 2009).
glioma (1 paper, 2023). A benign or malignant brain and spinal cord tumor that arises from glial cells (astrocytes, oligodendrocytes, ependymal cells). "However, the functions and mechanisms of CYB5D1 in cancers, including glioma, are still unknown." (PMID 36305248, 2023).
osteosarcoma (1 paper, 2015). A usually aggressive malignant bone-forming mesenchymal neoplasm, predominantly affecting adolescents and young adults. "Across all Ewing and osteosarcoma cell lines eleven genes were found to be either significantly (P < 0.05, Bonferroni correction) repressed (KIF20A, IDH1, SCD, GPSM2, EIF2AK4, HIBCH) or induced (STK19, DNAJC24, MTG2, FAM175B, CYB5D1) following non DNA-damaging XI-006 treatment (0.5 μM)." (PMID 26095524, 2015).
cancer (3 papers, 2009 to 2023). A tumor composed of atypical neoplastic, often pleomorphic cells that invade other tissues. "Our findings about CYB5D1 call into question the current paradigm that composite gene signatures perform better than one-gene signatures in cancer disease outcome prognosis." (PMID 19851466, 2009). "In fact, CYB5D1 was already decribed in the study of breast and other cancer but its expression levels negatively correlates with patients survival, suggesting an opposing effects, which may be tumor-type specific." (PMID 26359356, 2015). "CYB5D1 was already mentioned in breast and other types of cancer studies (see results section)." (PMID 19851466, 2009).
tumor (1 paper, 2015). "Another noteworthy gene is CYB5D1, which encodes for a protein belonging to the family of Hpr6, which was found to increase the resistance of tumor cells to DNA damaging agents." (PMID 26359356, 2015).
CYB5D1 also shares sentences with these, for which no sentence is quoted: colon cancer (1 paper).